MEOX1 (mesenchyme homeobox 1)
Description:
Mesodermal transcription factor that plays a key role in somitogenesis and is specifically required for sclerotome development. Required for maintenance of the sclerotome polarity and formation of the cranio-cervical joints. Binds specifically to the promoter of target genes and regulates their expression. Activates expression of NKX3-2 in the sclerotome. Activates expression of CDKN1A and CDKN2A in endothelial cells, acting as a regulator of vascular cell proliferation. While it activates CDKN1A in a DNA-dependent manner, it activates CDKN2A in a DNA-independent manner. Required for hematopoietic stem cell (HSCs) induction via its role in somitogenesis: specification of HSCs occurs via the deployment of a specific endothelial precursor population, which arises within a sub-compartment of the somite named endotome.
Synonyms: MOX1; KFS2
Tractability: No criterion of Open Targets' tractability assessment is met for any kind of drug.
Gene: Protein-coding gene on chromosome 17 (43,640,389 to 43,661,922, reverse strand). Ensembl gene ENSG00000005102.
Subcellular location: Nucleus; Cytoplasm
Subcellular location (Human Protein Atlas): Nucleoplasm; Cytokinetic bridge; Cytosol
Gene Ontology:
Molecular function: protein binding; sequence-specific double-stranded DNA binding; DNA-binding transcription factor activity; DNA-binding transcription factor activity, RNA polymerase II-specific; RNA polymerase II cis-regulatory region sequence-specific DNA binding; sequence-specific DNA binding; chromatin binding; DNA binding; DNA-binding transcription activator activity, RNA polymerase II-specific; HMG box domain binding
Biological process: hematopoietic stem cell differentiation; regulation of transcription by RNA polymerase II; sclerotome development; somite development; positive regulation of transcription by RNA polymerase II; regulation of DNA-templated transcription
Cellular component: chromatin; cytoplasm; nucleus
Genetic constraint (gnomAD): Loss-of-function variants: 16 observed, 21.28 expected, observed/expected ratio (o/e) 0.75, 90% interval 0.51 to 1.14. The upper end of that interval is the gene's LOEUF score, 1.14, which puts it in group 5 of 6, group 1 being the genes least tolerant of losing a copy. Missense variants: 330 observed, 323.99 expected, observed/expected ratio (o/e) 1.02, 90% interval 0.93 to 1.12. Synonymous variants: 132 observed, 131.37 expected, observed/expected ratio (o/e) 1, 90% interval 0.87 to 1.16.
Homologues: Orthologues: chimpanzee MEOX1 (99% identical), macaque MEOX1 (96% identical), dog MEOX1 (89% identical), pig MEOX1 (89% identical), rabbit MEOX1 (87% identical), mouse Meox1 (81% identical), rat Meox1 (81% identical), guinea pig MEOX1 (68% identical), zebrafish meox1 (54% identical), Drosophila melanogaster btn (26% identical). Paralogues in human: MEOX2 (48% identical).
Diseases named in the same sentence as MEOX1 in open-access papers:
MEOX1 is named in the same sentence as 37 diseases in open-access papers, as found by Europe PMC text mining. Sharing a sentence is not in itself a finding about the gene and the disease. The quoted sentences say what the papers report.
lung carcinoma (7 papers, 2013 to 2025). "MEOX1 shows a positive correlation with the overall survival of lung cancer patients, particularly those with lung adenocarcinoma." (PMID 38180753, 2024). "Nonetheless, a more recent investigation has demonstrated that MEOX1 is downregulated in lung cancer and serves as an anti-carcinogenic gene." (PMID 38486335, 2024). "Further investigations have revealed that MEOX1 suppresses the progression of lung cancer cells by inhibiting the cell cycle checkpoint gene CCNB1." (PMID 38180753, 2024). "Previous studies have indicated that MEOX1 exhibits lower expression in lung cancer tissues compared to normal adjacent tissues." (PMID 38180753, 2024). "Recent studies have reported that MEOX1 plays an important role in breast cancer, ovarian cancer, and lung cancer." (PMID 35860577, 2022). "MEOX1 plays a role in the molecular signaling network regulating somite development and promotes tumor progression in lung cancer and prostate cancer." (PMID 33952272, 2021). "ChIP-seq data from the ENCODE project indicate that both NRCAM and GPR56 contain binding sites for GRα, NF-κB and AP-1, while MEOX1 contain GRα and AP-1 sites in A549 lung cancer." (PMID 23593176, 2013). "The potential detection of Meox1 as a circulating biomarker could significantly advance applications in early-stage lung cancer diagnosis." (PMID 40919158, 2025). "Furthermore, PIK3C2G, FIBIN, CHRNA1, NPNT, MEOX1, and POU2F2 linked obesity and lung cancer, while PTPRQ, SSUH2, CILP2, CDH2, ABCA12, CPXM1, and L1CAM linked hypertension and lung cancer." (PMID 36685671, 2023). "Furthermore, researchers have found a negative correlation between MEOX1 and CCNB1 mRNA expression in various lung cancer tissues." (PMID 38180753, 2024).
ovarian carcinoma (7 papers, 2012 to 2025). A malignant neoplasm originating from the surface ovarian epithelium. "Through data mining from The Cancer Genome Atlas (TCGA) and Gene Expression Omnibus (GEO) databases, we have identified MEOX1 as a specific gene associated with LNM in ovarian cancer." (PMID 38486335, 2024). "The expression of MEOX1 was found to be relatively high in serous ovarian adenocarcinoma, and its higher expression were associated with increased tumor grade and poorer clinical prognosis for ovarian cancer patients." (PMID 38486335, 2024). "As anticipated, our bioinformatics analysis revealed that MEOX1 was not only associated with malignant behaviors of ovarian cancer such as tumor proliferation and EMT, but also closely linked to lymphangiogenesis, lymphatic vessels during metastasis, and degradation of ECM." (PMID 38486335, 2024). "Furthermore, bioinformatics analyses hinted at the possibility that MEOX1 might be implicated in the LNM of ovarian cancer by regulating tumor proliferation, tumor EMT, lymphangiogenesis, and ECM remodeling." (PMID 38486335, 2024). "The TCGA ovarian cancer cases were divided into two groups based on MEOX1 expression level: MEOX1 high expression and MEOX1 low expression groups, and then the DEGs between these two groups were obtained (Figure." (PMID 38486335, 2024). "The results of our study indicate that MEOX1 plays a role in the lymph node metastasis of ovarian cancer by regulating multiple biological activities, including the proliferation and EMT of ovarian cancer, lymphangiogenesis, and ECM remodeling." (PMID 38486335, 2024). "Bioinformatics analysis revealed that MEOX1 exhibited the highest mRNA levels among all cancer types in ovarian cancer tissues and cell lines." (PMID 38486335, 2024). "Analysis of public databases revealed a positive correlation between the mRNA expression of MEOX1 and the tumor grade of ovarian cancer (Figure." (PMID 38486335, 2024). "In this study, we first conducted an examination of the expression of MEOX1 in ovarian cancer and its correlation with LNM using bioinformatics methods, cell lines, and clinical specimens." (PMID 38486335, 2024). "In conclusion, we identified MEOX1 as a novel LNM-related biomarker in ovarian cancer by mining the TCGA and GEO databases." (PMID 38486335, 2024). "To preliminarily investigate the function and mechanism of MEOX1 in ovarian cancer LNM, we performed gene set enrichment analysis (GSEA) using the expression profiles of TCGA ovarian cancer." (PMID 38486335, 2024). "Subsequently, we performed further investigations to explore the impact of MEOX1 on the biological activities of ovarian cancer cells both in vitro and in vivo." (PMID 38486335, 2024). "In the present study, we screened out an LNM-related molecule in ovarian cancer, mesenchyme homeobox 1 (MEOX1), through data mining from the Cancer Genome Atlas TCGA (TCGA) and Gene Expression Omnibus (GEO) databases." (PMID 38486335, 2024). "To demonstrate the overexpression of MEOX1 in ovarian cancer, we initially examined the mRNA and protein expression of MEOX1 in the normal ovarian epithelial cell IOSE-80 and ovarian cancer cell lines (OVCAR5, HO8910, A2780, and SKOV3)." (PMID 38486335, 2024). "Based on these findings, we conclude that MEOX1 is overexpressed in the nucleus of ovarian cancer tumor cells and is associated with LNM in ovarian cancer." (PMID 38486335, 2024). "Since the “EMT pathway” had the highest enrichment score based on the GSEA analysis of MEOX1 in ovarian cancer, we continued to determine the in vitro effect of MEOX1 on the EMT of ovarian cancer cells." (PMID 38486335, 2024). "In ovarian cancer, MEOX1 has been reported to function as a cofactor of pre-B-cell leukemia homeobox-1 (PBX1), mediating the cancer-promoting biological behavior of PBX1." (PMID 38486335, 2024).
ovarian carcinoma (continued). "We found that upregulation of MEOX1 in ovarian cancer was associated with LNM, high G stage, and an unfavorable prognosis; functional experiments showed that MEOX1 promoted the proliferation and EMT of ovarian cancer cells." (PMID 38486335, 2024). "Subsequently, we explored the biological effect of MEOX1 on the proliferation of ovarian cancer cells." (PMID 38486335, 2024). "Our result showing that MEOX1 expression reversed the growth inhibitory effect of PBX1 knockdown suggests that MEOX1 mediates the growth-supporting function of PBX1 in ovarian cancer cells." (PMID 22567123, 2012). "The fact that MEOX1 is co-upregulated with PBX1 in a subset of ovarian carcinomas suggests that a PBX1-MEOX1 molecular axis is involved in the transcriptional regulation of these carcinomas." (PMID 22567123, 2012). "Recently, overexpression of mesenchyme homeobox 1 (MEOX1), a transcriptional factor controlling somite development, has been found to be involved in the occurrence and progression of ovarian cancer by regulating proliferation and EMT of cancer cells, lymphangiogenesis, and ECM remodeling." (PMID 41511312, 2025). "Our findings suggest that MEOX1 could serve as a potential biomarker for the diagnosis and treatment of ovarian cancer with LNM." (PMID 38486335, 2024). "The evidence presented above suggested that the anomalous overexpression of MEOX1 may reflect the lymph node metastasis potential of ovarian cancer cells and could be a crucial molecular event in the progression of the disease." (PMID 38486335, 2024). "However, the specific role and mechanism of MEOX1 in ovarian cancer, particularly in LNM, remain obscure and require further investigation." (PMID 38486335, 2024). "Conversely, the overexpression of MEOX1 in ovarian cancer and its correlation with an unfavorable prognosis suggested that MEOX1 might function as an oncogene in ovarian cancer." (PMID 38486335, 2024). "Interestingly, we noticed that ovarian cancer exhibited the highest median mRNA expression of MEOX1 compared to other cancer types (Figure." (PMID 38486335, 2024). "Based on these findings, we propose that MEOX1 may play a role in the occurrence and progression of ovarian cancer." (PMID 38486335, 2024). "Additionally, the expression of MEOX1 was positively correlated with the expression of numerous prolymphangiogenic factors in ovarian cancer." (PMID 38486335, 2024). "Consistent with the results of bioinformatics analysis, we demonstrated that the mRNA and protein levels of MEOX1 were higher in clinical ovarian cancer specimens and ovarian cancer cell lines than in normal ovarian tissues and the normal ovarian epithelial cell line IOSE-80, respectively." (PMID 38486335, 2024). "In addition, Meox1 was overexpressed in ovarian cancer cells along with Pbx1, and the silencing effects of Pbx1 were reversed by Meox1 expression in the cell lines." (PMID 33402862, 2020). "Furthermore, the mRNA expression of MEOX1 increased with higher tumor grade in ovarian cancer." (PMID 38486335, 2024). "Notably, the expression level of MEOX1 was substantially higher in LNM+ ovarian cancer tissues compared to LNM- ovarian cancer tissues, providing additional evidence that the expression of MEOX1 had a certain predictive value in determining the presence of LNM." (PMID 38486335, 2024). "Remarkably, we observed that MEOX1 was overexpressed in tumor tissues of ovarian cancer, and the expression of MEOX1 in ovarian cancer tissues and cell lines ranked first among all cancer types, suggesting that MEOX1 may play a greater role in the occurrence and development of ovarian cancer." (PMID 38486335, 2024). "Among the ovarian cancer cell lines, SKOV3 cells had relatively low expression of MEOX1, while A2780 cells had relatively high expression (Figure." (PMID 38486335, 2024).
ovarian carcinoma (continued). "Our findings revealed MEOX1 as a novel LNM-related gene in ovarian cancer, which can predict the occurrence of LNM and poor clinical prognosis in ovarian cancer patients." (PMID 38486335, 2024). "However, further functional experiments are required to determine the specific function of MEOX1 in promoting LNM in ovarian cancer and whether MEOX1, as a transcription factor, promotes lymphangiogenesis by regulating the expression of prolymphangiogenic factors of ovarian cancer cells." (PMID 38486335, 2024). "Previous studies have demonstrated that PBX1 was essential for cell growth in ovarian cancer cells including OVCAR3; here, we performed siRNA knockdown to determine if MEOX1 knockdown produced a phenotype similar to PBX1 knockdown." (PMID 22567123, 2012). "Moreover, our fundamental experiments demonstrated that suppression of MEOX1 led to inhibitory effects on ovarian cancer cell proliferation and EMT, while overexpression of MEOX1 enhanced the proliferation and EMT capacities of ovarian cancer cells." (PMID 38486335, 2024). "From this perspective, it would be important to determine if MEOX1 modulates the selectivity and target sequence binding affinity of the PBX1 transcription complex in ovarian cancer, and ultimately, it would be interesting to determine how PBX1/MEOX1 complex formation promotes oncogenesis." (PMID 22567123, 2012). "Since overexpression of PBX1 and MEOX1 is relatively specific to ovarian cancer as compared to other solid tumors, the biological significance of PBX1 and MEOX1 co-expression and their cooperation in transcriptional regulation are likely to be context- and tissue-dependent." (PMID 22567123, 2012). "The ROC analysis revealed that both MEOX1 (AUC = 0.887, Confidence interval (CI) = 0.849 - 0.926) and SPP1 (AUC = 0.988, CI = 0.979 - 0.997) expression could serve as single significant parameters for discriminating between normal and tumor tissues of ovarian cancer (Figure." (PMID 38486335, 2024).
breast carcinoma (5 papers, 2016 to 2024). "Functional gene set enrichment analysis and siRNA knockdown of several candidate genes revealed a set of homeobox transcription factors (specifically MEOX1) as novel potential targets in the PTEN-deficient trastuzumab-resistant breast cancer cells." (PMID 27285982, 2016). "MEOX1 was associated with poor survival, lymph node metastasis, and stage of breast cancer patients." (PMID 27285982, 2016). "The analyses revealed that Nuclear MEOX1 expression level (p=0.042), with a Hazard Ratio (HR) of 2.19 and a 95% CI of 1.029-4.669, was an independent prognostic factor in breast cancer patients." (PMID 27285982, 2016). "In order to investigate the potential clinical implications of MEOX1 in breast cancer patients, we performed immunohistological staining of MEOX1 in a breast cancer tissue microarray (TMA) containing tumor samples and associated survival data (N=150)." (PMID 27285982, 2016). "In particular, MEOX1 is correlated with poor survival of breast cancer patients." (PMID 30704450, 2019). "Together, this data suggests that there may be direct regulation of MEOX1 by the HER2 signaling cascade beyond the context of trastuzumab resistant HER2+ breast cancers." (PMID 27285982, 2016). "Statistical analysis indicated that positive MEOX1 nuclear staining was associated with poor survival of breast cancer patients compared to patients with negative nuclear staining (P =0.019)." (PMID 27285982, 2016).
lymph node metastasis (4 papers, 2016 to 2026). "In tumor biopsies MEOX1 is associated with poor patient survival, lymph node metastasis, and higher cancer stages." (PMID 27285982, 2016). "Although, the significant correlation between risk genes MEOX1, COL17A1, and lymph-node metastasis in triple-negative breast cancer patients has been reported." (PMID 37178414, 2023). "In addition, MEOX1 nuclear staining was significantly correlated with the presence of Lymph node metastasis and cancer stage (P<0.05)." (PMID 27285982, 2016).
asthma (3 papers, 2021 to 2025). "SNPs located between ETV4 and mesenchyme homeobox 1 (MEOX1) were significantly associated with adult asthma, including rs4792901 and rs2880540 (P = 5.63E−5 and 2.77E−5, respectively)." (PMID 34552174, 2021). "In conclusion, we have demonstrated that two eQTLs in the ETV4/MEOX1 region, rs4792901 and rs2880540, showed a significant association with the development of adult asthma in Japanese." (PMID 34552174, 2021). "These two SNPs were correlated with mRNA expression levels of ETV4 and Mesenchyme Homeobox 1 (MEOX1); asthma risk alleles at the two SNPs showed increased levels of mRNA expression of these genes." (PMID 34552174, 2021). "There was a cluster of six SNPs significantly associated with asthma between the ETV4 and MEOX1 genes." (PMID 34552174, 2021). "In addition to ETV4, MEOX1 (located in the vicinity of ETV4) is also a candidate molecule for the development of asthma via the Th17 pathway." (PMID 34552174, 2021). "Although ETV4 has not been detected in any genetic studies of asthma to date, in the present study, we successfully identified eQTLs for ETV4/MEOX1 genes at 17q21.31 as significantly associated with adult asthma." (PMID 34552174, 2021). "Given that rs2880540, an eQTL for MEOX1 as well as for ETV4, was associated with asthma independent of rs4792901, and the haplotype consisting of the two SNPs showed the strongest association with asthma, the combined effect of both genes may explain the findings in the current study." (PMID 34552174, 2021).
fibrosis (3 papers, 2020 to 2026). the formation of excess fibrous connective tissue in an organ or tissue in a reparative or reactive process. "We aimed to explore the role of Meox1 in cardiac fibrosis and remodeling post-MI and its underlying mechanisms." (PMID 41362745, 2026). "Knockdown of Meox1 in Myofbs remarkably attenuated cardiac fibrosis and adverse remodeling post-MI and improved cardiac function." (PMID 41362745, 2026). "Therefore, Meox1/Cthrc1/p-Smad2/3 signaling pathway might be a promising therapeutic target for cardiac fibrosis and remodeling in MI patients." (PMID 41362745, 2026). "In summary, our study reveals that MEOX1 expression is upregulated following AMI and, as a downstream target of TGF-β1, MEOX1 can inhibit angiogenesis and promote cardiac fibrosis post-AMI in vitro via EndoMT induction." (PMID 38431730, 2024).
Klippel-Feil syndrome (3 papers, 2013 to 2023). A congenital, musculoskeletal condition characterized by the fusion of at least two vertebrae of the neck. "Frameshift mutations resulting in an unstable MEOX1 transcript or nonsense mutations of MEOX1 have been described to cause Klippel-Feil-Syndrome, a segmentation defect in the cervical spine." (PMID 37559728, 2023). "In patients, homozygous truncation mutations in the MEOX1 gene cause an autosomal-recessive form of Klippel-Feil Syndrome, a disease characterized by fusion of cervical vertebrae." (PMID 27285982, 2016).